RNU6-208P (RNA, U6 small nuclear 208, pseudogene)
Gene: Small nuclear RNA gene on chromosome 16 (71,666,091 to 71,666,197, forward strand). Ensembl gene ENSG00000199301.
Homologues: Orthologues: chimpanzee U6 (97% identical), dog U6 (87% identical), macaque U6 (87% identical), dog U6 (81% identical). Paralogues in human: RNU6-16P (90% identical), RNU6-11P (89% identical), RNU6-37P (89% identical), RNU6-812P (89% identical), RNU6-10P (88% identical), RNU6-17P (88% identical), RNU6-18P (88% identical), RNU6-393P (88% identical), RNU6-41P (88% identical), RNU6-45P (88% identical), RNU6-921P (88% identical), RNU6-1 (87% identical), and 1286 more.